HEBP1 (heme binding protein 1)
Description:
May bind free porphyrinogens that may be present in the cell and thus facilitate removal of these potentially toxic compound. Binds with a high affinity to one molecule of heme or porphyrins. It binds metalloporphyrins, free porphyrins and N-methylprotoporphyrin with similar affinities.
Synonyms: HBP; HEBP
Tractability: Antibody: its Gene Ontology location is reachable by antibodies, with high confidence. PROTAC: ubiquitination databases record sites on it; its protein half-life has been measured.
Gene: Protein-coding gene on chromosome 12 (12,974,867 to 13,000,275, reverse strand). Ensembl gene ENSG00000013583.
Subcellular location: Cytoplasm
Subcellular location (Human Protein Atlas): Vesicles; Nucleoplasm
Pathways (Reactome):
Signal Transduction: Formyl peptide receptors bind formyl peptides and many other ligands; G alpha (i) signalling events
Gene Ontology:
Molecular function: heme binding
Biological process: circadian rhythm
Cellular component: extracellular exosome; mitochondrion; extracellular region; cytoplasm
Genetic constraint (gnomAD): Loss-of-function variants: 12 observed, 19.03 expected, observed/expected ratio (o/e) 0.63, 90% interval 0.4 to 1.02. The upper end of that interval is the gene's LOEUF score, 1.02, which puts it in group 4 of 6, group 1 being the genes least tolerant of losing a copy. Missense variants: 234 observed, 255.66 expected, observed/expected ratio (o/e) 0.92, 90% interval 0.82 to 1.02. Synonymous variants: 91 observed, 94.25 expected, observed/expected ratio (o/e) 0.97, 90% interval 0.81 to 1.15.
Homologues: Orthologues: chimpanzee HEBP1 (100% identical), macaque HEBP1 (99% identical), rabbit HEBP1 (91% identical), guinea pig HEBP1 (89% identical), mouse Hebp1 (87% identical), rat Hebp1 (87% identical), pig HEBP1 (85% identical), tropical clawed frog hebp1 (51% identical). Paralogues in human: HEBP2 (25% identical).
Diseases named in the same sentence as HEBP1 in open-access papers:
HEBP1 is named in the same sentence as 21 diseases in open-access papers, as found by Europe PMC text mining. Sharing a sentence is not in itself a finding about the gene and the disease. The quoted sentences say what the papers report.
Alzheimer disease (5 papers, 2019 to 2023). A progressive, neurodegenerative disease characterized by loss of function and death of nerve cells in several areas of the brain leading to loss of cognitive function such as memory and language. "Taken together, these results support our findings that Hebp1 is indeed a novel protein dysregulated in Alzheimer’s disease that is particularly associated with severe AD cases." (PMID 31453805, 2019). "The only other protein significantly upregulated in Alkbh7-/- was heme binding protein 1 (Hebp1), and notably a recent study found both GLO-1 and Hebp1 were upregulated in Alzheimer’s disease, suggesting these proteins may share a common upstream regulator." (PMID 32795389, 2020). "We thus further investigated the function of Hebp1 and its potential role in Alzheimer’s disease." (PMID 31453805, 2019).
breast carcinoma (1 paper, 2024). "Another study also found that HEBP1 expression levels significantly affected the development of bone metastasis from breast cancer." (PMID 39119575, 2024).
cholelithiasis (1 paper, 2025). The presence of crystallized deposits forming in the gallbladder or biliary tree, primarily composed of cholesterol, bilirubin, and bile. "Specifically, the expression of the following genes was associated with a decreased risk of cholelithiasis: HEBP1 (OR = 0.92, 95% CI = 0.89–0.96) and MTO1 (OR = 0.94, 95% CI = 0.91–0.97), suggesting that these genes may be related to a reduced risk of cholelithiasis." (PMID 40958306, 2025). "This study, through multi-omics integrative analysis, provides the first evidence of a causal link between mitochondrial-related genes (LIAS, TARS2, HEBP1, PNKD) and cholelithiasis, and evaluates their potential as viable drug targets." (PMID 40958306, 2025). "Similarly, methylation at cg12479139 in HEBP1 (OR = 0.839, 95% CI = 0.768–0.916) and at cg05991184 in PNKD (OR = 0.766, 95% CI = 0.693–0.847) were also protective factors against cholelithiasis." (PMID 40958306, 2025). "This study, using the SMR and HEIDI testing methods, investigated the association of genetically predicted mitochondrial-related gene methylation, gene expression, and cholelithiasis, identifying 4 potential drug targets for cholelithiasis: TARS2, LIAS, HEBP1, and PNKD." (PMID 40958306, 2025). "Through multi-omics integration, we have constructed for the first time a causal pathway linking mitochondrial-related genes, metabolic pathways, and cholelithiasis, providing theoretical support for personalized therapies targeting the genes LIAS, TARS2, HEBP1, and PNKD." (PMID 40958306, 2025).
emotionally unstable personality disorder (1 paper, 2024). "Particularly noteworthy was the risk effect of HEBP1 on clinical traits such as tooth eruption problems, emotionally unstable personality disorder, and encephalopathy." (PMID 39119575, 2024).
gout (1 paper, 2024). A condition characterized by painful swelling of the joints, which is caused by deposition of urate crystals. "For instance, HEBP1 was associated with decreased risk of other secondary gout (OR, 0.34, 95% CI, 0.18 to 0.61, p = 4.08 × 10−4) and hallux rigidus (OR, 0.88, 95% CI, 0.81 to 0.95, p = 2.16 × 10−3)." (PMID 39119575, 2024).
melanoma (1 paper, 2024). A malignant, usually aggressive tumor composed of atypical, neoplastic melanocytes. "For example, of the 16 total genes driving the association between melanoma and nevus count, only two (MTAP and ERVFRD‐3) were shared by all three tissues, and six (MAFF, HEBP1, HTR7P1, EMP1, GPRC5A, C9orf66) were specific to melanocyte." (PMID 38308491, 2024).
neuroblastoma (1 paper, 2017). Neuroblastoma (NB) is the most common solid, extracranial childhood tumor. "Similar to the previous findings in Pink1−/− mice, an upregulation of RSAD2 and a downregulation of HEBP1 were observed in the starving PINK1-deficient neuroblastoma cells." (PMID 28768533, 2017).
neurovascular disorder (1 paper, 2023). A disorder of the nervous system related to a vascular etiology. "Our study provides new insights into the function of Hebp1, not only in the context of peripheral nerve disease, but also in the setting of other neurovascular disorders." (PMID 37324943, 2023).
osteonecrosis (1 paper, 2024). A none disease characterized by death of bone tissue due to a lack of blood supply. "To avoid the potential type I error, we further conducted the FDR method to adjust the p-value and found that Heme-binding protein 1 (HEBP1) was positively associated with osteonecrosis risk (OR = 1.40, 95% CI, 1.19 to 1.65, p = 3.96 × 10−5, PFDR = 0.044)." (PMID 39119575, 2024). "Meanwhile, more evidence demonstrating the effect of HEBP1 on osteonecrosis risk was obtained using MR-Egger, weighted median, and weighted mode." (PMID 39119575, 2024). "To comprehensively explore the health effect of HEBP1, which was found to be associated with osteonecrosis risk, we conducted a PheWAS-MR association analysis, screening 2,406 traits from the Finnish GWAS (version 10)." (PMID 39119575, 2024). "Our findings revealed that HEBP1 was associated with 136 phenotypes excluding osteonecrosis (p < 0.05)." (PMID 39119575, 2024). "Future studies further validate the association by examining whether anti-HEBP1/ALDH3A1 therapeutic antibodies have a role in osteonecrosis." (PMID 39119575, 2024). "The causal association between HEBP1 and osteonecrosis risk." (PMID 39119575, 2024). "Notably, Heme-binding protein 1 (HEBP1) was significant positively associated with osteonecrosis risk with convening evidence (OR, 1.40, 95% CI, 1.19 to 1.65, P = 3.96 × 10−5, PFDR = 0.044)." (PMID 39119575, 2024). "However, our study identifies a positive association between HEBP1 and osteonecrosis risk." (PMID 39119575, 2024). "This comprehensive MR study identifies 71 plasma proteins associated with osteonecrosis, with HEBP1, ITIH1, SMOC1, and CREG1 showing potential as biomarkers of osteonecrosis." (PMID 39119575, 2024). "In this study, we identified 30 plasma proteins positively associated with osteonecrosis, and in particular, HEBP1 significantly increased the risk of osteonecrosis and ALDH3A1 suggestive increased the risk of osteonecrosis." (PMID 39119575, 2024). "In conclusion, this study demonstrated a causal link between multiple plasma proteins and osteonecrosis through a comprehensive MR analysis, especially HEBP1, which provides a new pathway for the biological mechanism of osteonecrosis and helps to explore early intervention and treatment." (PMID 39119575, 2024). "Despite the lack of pharmacological information on HEBP1 and ALDH3A1, it remains a promising prognostic biomarker and therapeutic marker for osteonecrosis." (PMID 39119575, 2024).
osteoporosis (1 paper, 2019). A condition of reduced bone mass, with decreased cortical thickness and a decrease in the number and size of the trabeculae of cancellous bone (but normal chemical composition), resulting in increased fracture incidence. "The genes identified in our study—LTBP1, PZP, ARID2, and HEBP1 in osteoporosis BRON patients—clearly support the previous evidence that angiogenesis, osteoclast activity, bone remodeling, and immune responses are critical underlying mechanisms." (PMID 31747953, 2019). "Excluding genes without known specific functions (CDC27 and TNRC18), ARID2, HEBP1, LTBP1, and PLVAP were the only significant differences in the cancer group revealed by the gene-score methodology, while DFFA, FAM193A, and VEGFA were the only significant differences in the osteoporosis group." (PMID 31747953, 2019).
peripheral nerve injuries (1 paper, 2023). "Our findings provide new insights into Hebp1 as a neurovascular regeneration factor and demonstrate its potential therapeutic application to various peripheral nerve injuries." (PMID 37324943, 2023).
psoriasis (1 paper, 2023). An autoimmune condition characterized by red, well-delineated plaques with silvery scales that are usually on the extensor surfaces and scalp. "The expression levels of phospholipid scramblase 1 (PLSCR1), heme binding protein 1 (HEBP1), structural maintenance of chromosomes 4 (SMC4), and RuvB like AAA ATPase 1 (RUVBL1) genes were shown to be reversed by candidate compounds for psoriasis using the RORUCI values." (PMID 37035327, 2023).
infection (2 papers, 2021 to 2023). The state of being infected such as from the introduction of a foreign agent such as serum, vaccine, antigenic substance or organism. "Expression of CMA genes during infection of these cell lines was also examined (right 12 lanes), and demonstrated that reduction in GRIM-19 level did not influence the level of transcription of any of the four CMA genes tested (TPM3, STX3, Dystroglycan 1 [DAG1], and Heme-binding protein 1 [HEBP1])." (PMID 34346763, 2021).
cancer (1 paper, 2019). A tumor composed of atypical neoplastic, often pleomorphic cells that invade other tissues. "The HEBP1 gene identified in three BRONJ cancer patients is very interesting as well." (PMID 31747953, 2019). "In the cancer group, ARIDS, HEBP1, LTBP1, and PLVAP were identified as candidate genes." (PMID 31747953, 2019).
neurodegenerative disease (1 paper, 2024). A disorder of the central nervous system characterized by gradual and progressive loss of neural tissue and neurologic function. "Recent studies have shown the importance of HEBP1 in the central nervous system, particularly in neurodegenerative diseases." (PMID 39119575, 2024).
tumor (1 paper, 2021). "Although alterations of several genes (such as Hebp1, Eno1, and Taf9) other than Ankrd52 are more frequently detected in our tumor profiling, their targeting sgRNAs exhibited much less enrichment or fold-change as compared to those of Ankrd52." (PMID 34853298, 2021).
HEBP1 also shares sentences with these, for which no sentence is quoted: diabetes (1 paper); Encephalopathy (1); Hallux rigidus (1); nevus (1); peripheral nerve disease (1).